RN7SL598P (RNA, 7SL, cytoplasmic 598, pseudogene)
Gene: Miscellaneous RNA gene on chromosome 14 (58,179,771 to 58,180,064, forward strand). Ensembl gene ENSG00000243700.
Homologues: Orthologues: chimpanzee Metazoa_SRP (99% identical), macaque Metazoa_SRP (88% identical). Paralogues in human: RN7SL2 (84% identical), RN7SL1 (83% identical), RN7SL3 (82% identical), RN7SL147P (80% identical), RN7SL326P (80% identical), RN7SL230P (80% identical), RN7SL296P (79% identical), RN7SL444P (79% identical), RN7SL321P (79% identical), RN7SL448P (79% identical), RN7SL126P (79% identical), RN7SL278P (79% identical), and 701 more.